CX3CL1 (C-X3-C motif chemokine ligand 1)
Diseases named in the same sentence as CX3CL1 in open-access papers (continued):
Sharing a sentence is not in itself a finding about the gene and the disease.
dementia (11 papers, 2005 to 2025). Loss of intellectual abilities interfering with an individual's social and occupational functions. "Our demonstration that CX3CL1 mRNA expression is induced in astrocytes within EAE lesions is novel although the data are in accordance with study of humans with HIV-associated dementia where CX3CL1 immunoreactivity was detected in astrocytes." (PMID 16053521, 2005). "Urinary CX3CL1’s potential as an early biomarker holds diagnostic and prognostic significance, reflecting changes across the AD spectrum, from preclinical to prodromal and dementia stages." (PMID 39917031, 2025). "In the ε3 stratum, TNFB, CDCP1, and CX3CL1 were significantly associated with incident dementia." (PMID 37584418, 2023). "Associations between the tested biomarkers (CXCL12, CX3CL1, YKL-40, Ng, and NPTXR), cognitive status, and neurochemical dementia biomarkers of AD were compared." (PMID 37685973, 2023). "We identified four biomarker clusters, among which the strongest representatives, CX3CL1, EN-RAGE, LAP TGF-beta-1, and VEGF-A, were significantly associated with dementia endpoints independently from other inflammation-related proteins." (PMID 36085081, 2022). "Here, we show for the first time that neuronal CX3CL1 is decreased in the CSF samples from AD dementia patients compared to those from control subjects." (PMID 30245615, 2018). "Here, we report a decrease in CX3CL1 in the CSF of AD dementia patients compared to that of control subjects." (PMID 30245615, 2018). "This increase is reflected by a decrease in the secretion of soluble CX3CL1 into the CSF of AD dementia patients compared to controls and MCI subjects." (PMID 30245615, 2018). "The results show that CSF chemokine concentration of MCP-1/CCL2, MIP-1α/CCL3, MIP-1β/CCL4, RANTES/CCL5, IL-8/CXCL8 and fractalkine/CX3CL1 is positively correlated with the severity of dementia and the viral load, indicating HIV induced brain damage." (PMID 16712719, 2006). "Along with the progression of dementia, urinary CX3CL1 levels increased with the progression of AD." (PMID 39917031, 2025). "Whether the effect of CX3CL1 is neuroprotective or neurotoxic in diseases like dementia is still controversially discussed in the literature." (PMID 36085081, 2022). "The biomarkers CX3CL1, EN-RAGE, LAP TGF-beta-1, and VEGF-A had strong and independent associations with dementia outcomes and may have great potential as drug targets, early diagnostic markers, and components of dementia prediction scores." (PMID 36085081, 2022). "CX3CL1 was decreased in the CSF of AD dementia patients compared to control subjects." (PMID 30245615, 2018). "Furthermore, a clear decrease in CX3CL1 concentration was also found when control and AD dementia samples were compared (C = 0.31 ± 0.05 ng/ml vs. AD = 0.166 ± 0.05 ng/ml; ∗∗∗p < 0.0001)." (PMID 30245615, 2018). "Therefore, decreased levels of CX3CL1 are more evident in advanced stages (dementia)." (PMID 30245615, 2018). "Because the amount of CX3CL1 in CSF didn’t change in MCI compared to control subjects, we focus the measure on samples from control subjects and AD dementia patients." (PMID 30245615, 2018).
depression (11 papers, 2015 to 2023). "In a LPS-induced depression model, the decreased expression of CX3CL1 and microglial activation were observed in the HIP." (PMID 35668399, 2022). "The serum levels of CX3CL1 in patients with moderate–severe depression were higher than in the control group." (PMID 35668399, 2022). "A positive correlation between CX3CL1 levels and depression severity was observed in patients with colorectal cancers and comorbid depression." (PMID 33921690, 2021). "Based on our finding of CX3CL1 and others, further study should assess the interactions between CX3CL1 on neurons and CX3CR1 on microglia to reveal communication mechanisms of microglial regulation in neuroinflammation-associated depression." (PMID 30135647, 2018). "Prenatal stress seems to affect the fractalkine axis diversely since in an animal model of depression based on the prenatal stress procedure, the hippocampal and cortical levels of CX3CL1 and CX3CR1 are diminished and return to normal values during therapy with antidepressants." (PMID 33498837, 2021). "In this figure, chemokines (e.g., CX3CL1, CXCL12, CCL5) with direct neurotransmitter-like or neuromodulatory actions may directly influence neurotransmitter systems that are implicated in depression." (PMID 26441528, 2015). "Considering that CXCL12, CX3CL1 and their receptors play a crucial role in brain homeostasis and the course of pathological conditions, e.g., neuroinflammation, disturbances in these molecules expression, have been proposed as a potential background of brain disorders, including depression." (PMID 29163165, 2017). "The aim of this study was to test the relationship between depression and plasma concentrations of CCL2, CCL11, CX3CL1 and CXCL12 in mildly and moderately depressed primary-care patients, as well as the potential influence of an effective iCBT intervention on those molecules." (PMID 31974503, 2020).
heart failure (11 papers, 2014 to 2025). Inability of the heart to pump blood at an adequate rate to meet tissue metabolic requirements. "CX3CR1 and CX3CL1 expression is consistently upregulated in cardiac tissue from heart failure patients with various aetiologies, including end-stage DCM, according to our unpublished data." (PMID 37830591, 2023). "We have reported that CX3CL1 exacerbated heart failure and direct inhibition of CX3CL1 improved cardiac function." (PMID 35370759, 2022). "Because of its role in inflammatory pathways, CX3CL1 is recognized as an independent predictor of mortality among advanced heart failure patients." (PMID 29590257, 2018). "CX3CL1 is predominantly expressed by endothelial cells in myocardial ischemia and heart failure." (PMID 40936920, 2025). "In addition, we have demonstrated that CX3CL1 exacerbates heart failure and promotes cardiac remodeling in mice with myocardial ischemia or pressure overload." (PMID 35370759, 2022). "In a non-parasitic model, early β-adrenergic stimulation was shown to activate the cardiac CX3CL1/CX3CR1 axis, supporting transient concentric remodeling and delaying the progression to heart failure." (PMID 40936920, 2025).
Hypertension (11 papers, 2014 to 2025). The presence of chronic increased pressure in the systemic arterial system. "At 3 months of treatment, CX3CL1 levels were higher in patients with hypertension (1.1 ± 0.1 vs. 0.9 ± 0.1 ng/mL; p = 0.070) or metabolic syndrome (1.1 ± 0.1 vs. 0.9 ± 0.1 ng/mL; p = 0.047)." (PMID 35165326, 2022). "Taken together, these results indicate that CMS of VSMCs induces inflammation-related gene expression, including that of CXCL1 and CX3CL1, which may play important roles in the stress response against CMS caused by hypertension." (PMID 29170451, 2017). "In summary, AngII-induced hypertension associated with T. cruzi infection may act synergistically to increase TNF and CX3CL1 in the 2K1C rat model, thereby intensifying cardiac inflammatory infiltration and worsening the underlying inflammation triggered by this protozoan." (PMID 29590257, 2018). "Another study investigating AngII-induced hypertension in the context of T. cruzi infection revealed a synergistic effect of hypertension and T. cruzi infection on TNF and CX3CL1 expression, leading to enhanced leukocyte recruitment into cardiac tissue." (PMID 40936920, 2025). "In this study, we showed that CMS induces two chemokines, CXCL1 and CX3CL1, in a JNK-dependent manner and that CXCL1 is induced in hypertension by AAC." (PMID 29170451, 2017). "The comparison of OSA patients without any other diseases with OSA patients with only hypertension also demonstrated increased concentrations of CCL3 and, additionally, increased concentrations of CX3CL1/Fractalkine and IL-7." (PMID 36769452, 2023). "In this study, CXCL1 increased more obviously than CX3CL1 in RASMCs subjected to CMS, whereas Cxcl1, but not Cx3cl1, was increased in hypertension in vivo, suggesting that CMS in vitro mimics hypertension in vivo with regard to the expression of CXCL1 and CX3CL1." (PMID 29170451, 2017).
colon carcinoma (10 papers, 2007 to 2025). "Indeed, high serum concentrations of soluble CX3CL1 were associated with low T cell cytotoxicity while low serum concentrations of soluble CX3CL1 were associated with high T cell cytotoxicity at the tumor site in a mouse model of adoptive T cell therapy of colon carcinoma." (PMID 37771579, 2023). "It has also been recently shown that CX3CR1, the receptor for CX3CL1, is functionally required in TAMs to support angiogenesis and efficient formation of colon cancer liver metastases." (PMID 25882816, 2015). "We examined the expression of CX3CL1 in several colon cancer cell lines." (PMID 27096098, 2016). "This therapy is associated with enhanced CX3CL1 levels in human colon cancers, leading to the recruitment of non-classical monocytes to the vascular bed of the tumor, where they promote accumulation of neutrophils and immune suppression through IL-10 secretion." (PMID 30930117, 2019). "Additionally, CX3CL1/CX3CR1 signaling induces paclitaxel resistance in gastric cancer through RhoA signaling and promotes migration and resistance to anti-PD-1 therapy in colon cancer, and the blockade of CX3CL1/CX3CR1 has proven effective in both cases." (PMID 39409924, 2024).
diabetic nephropathy (10 papers, 2016 to 2024). "Moreover, the ADAM10-mediated shedding of CX3CL1 has been linked to diabetic nephropathy, where increased levels of soluble CX3CL1 contribute to kidney injury and fibrosis." (PMID 37762417, 2023). "The CX3CL1/CX3CR1 axis directly upregulates the expansion of mesangial cells in diabetes nephropathy through ROS and MAPK." (PMID 36969169, 2023). "The hyperglycaemia, formation of advanced glycation end products, and cytokine activation in the diabetic condition can induce overproduction of CX3CL1 in the kidneys and aggravate diabetic nephropathy." (PMID 27781209, 2016). "Fractalkine/CX3CL1 and its receptor CX3CR are upregulated during renal injury in several mouse models, including experimental folic acid nephropathy, crescentic GN, and diabetic nephropathy." (PMID 33986961, 2021). "Also, it is reported that the CX3CL1/CX3CR1 axis can up-regulate mesangial cell expansion directly via Reactive Oxygen Species (ROS) and Mitogen-Activated Protein Kinase (MAPK) in diabetic nephropathy (Park, Song & Ha, 2012)." (PMID 31355054, 2019).
ischemic stroke (10 papers, 2014 to 2025). A stroke disorder caused by obstruction of blood flow to the brain, due to thrombotic (local blood clot formation) or embolic (due to a blood clot or other material traveling from another site) event. "A previous study demonstrated that the expression of CX3CL1 and CX3CR1 is increased in rats early after ischemic stroke and that reducing the expression of CX3CL1 and CX3CR1 is beneficial for the recovery of neurological function." (PMID 32819407, 2020). "Consistent with a previous study in ischemic stroke mice, we found that the expression of both CX3CL1 and CX3CR1 increased significantly in the hippocampus of rats and that this effect was mimicked by knockdown of miR-195." (PMID 32819407, 2020). "We, therefore, looked into whether this reduced CX3CL1 on neuronsweakened its suppressive effects on the microglial inflammatory response,resulting in the worsened neurological injury after an ischemic stroke." (PMID 37908770, 2023). "Activation of the CX3CL1/CX3CR1 axis is neuroprotective in multiple neuroinflammatorydiseases, including ischemic stroke." (PMID 29692197, 2018). "Attenuation of CX3CL1 signaling by CX3CL1 or CX3CR1 gene knockdown both significantly reduced infarct size, expression of IL-1β and TNF-α, and leukocyte infiltration in ischemic stroke models." (PMID 26860080, 2016). "Tat‐CX3CL1 competitively blocks the PSD‐93–CX3CL1 interaction, attenuates microglial release of IL‐1β and TNF‐α, shifts microglia from a pro‐inflammatory M1 state to an anti‐inflammatory M2 phenotype, reduces infarct volume, and improves neurological outcomes in ischemic stroke models." (PMID 41367136, 2025).
liver fibrosis (10 papers, 2015 to 2025). "Our findings suggest that decreased concentrations of CX3CL1/Fractalkine are associated with an increased risk of progressive liver fibrosis, indicating the potential of this chemokine as a prognostic biomarker for the development of liver fibrosis." (PMID 39329945, 2024). "Our findings suggest that the decreased levels of CX3CL1/Fractalkine are associated with an increased risk of fibrosis progression, making it a potential prognostic marker for liver fibrosis development." (PMID 39329945, 2024). "In cases of severe liver fibrosis, CX3CL1/Fractalkine levels are significantly higher than those in healthy donors, as well as in HCV and autoimmune hepatitis patients, where the levels remain within the normal range." (PMID 39329945, 2024). "Second, we need to further explore the mechanisms of BMDMstgmif on liver fibrosis, such as attempting to neutralize CX3CL1 in vivo." (PMID 38247166, 2024). "The comparison showed a statistically significant depletion of CX3CL1/Fractalkine in the samples from HBV-infected individuals with severe liver fibrosis." (PMID 39329945, 2024). "In vivo research on the CX3CL1/CX3CR1 axis’s function in fibrosis revealed that CX3CL1/CX3CR1 signaling prevents macrophage-driven fibrogenesis in a hepatic fibrosis model." (PMID 37928902, 2023). "CX3CL1/Fractalkine is a key player in liver fibrosis formation." (PMID 39329945, 2024). "Interestingly, increased serum CX3CL1 level correlates with chronic liver diseases, such as liver fibrosis, and CX3CR1 regulates the differentiation and survival of infiltrating monocytes in the liver of mice to limit fibrosis." (PMID 30305672, 2018). "BMS-935177, an orally active small molecule inhibitor, selectively blocks CX3CL1/CX3CR1 interaction and reduces liver fibrosis in experimental NASH models." (PMID 41269996, 2025). "Even at the initial stages of liver fibrosis due to HBV, the CX3CL1/Fractalkine levels are reduced when compared to both HCV patients and healthy individuals." (PMID 39329945, 2024). "Mφtgmif effectively ameliorates liver fibrosis and deactivates aHSCs by recruiting Ly6Chi macrophages via paracrine CCL2 and polarizing them into the restorative Ly6Clo macrophage through the secretion of CX3CL1." (PMID 38247166, 2024). "The heat map showed that GXF could significantly inhibit the expression of some chemokine-related genes such as CCL2, CXCL6 and CX3CL1, suggesting that GXF may alleviate CCl4-induced liver fibrosis by inhibiting the recruitment of related immune cells." (PMID 35180857, 2022).
lupus nephritis (10 papers, 2015 to 2025). Glomerulonephritis in the context of systemic lupus erythematosus. "Previously, ISG20 has been reported to act as a mediator of CX3CL1 production, thereby inducing glomerular inflammation, particularly in patients with lupus nephritis." (PMID 40622935, 2025). "In addition, lupus nephritis showed functional and histological improvement after treatment with anti-CX3CL1, indicating a therapeutic effect of anti-CX3CL1." (PMID 40508161, 2025).
pancreatic cancer (10 papers, 2011 to 2024). "Recent reports in human pancreatic cancer cells indicated that, on these cells, CX3CL1 is a protector against apoptosis." (PMID 33391453, 2021). "In this publication, CX3CL1 directly promoted proliferation and therapy resistance of pancreatic cancer cells by leading to enrichment of pancreatic cancer cells in S phase with a concomitant decrease of the number of cells in G1 phase." (PMID 31561620, 2019). "Human surgical specimen from pancreatic cancer patients revealed a high expression of CX3CL1 compared to control tissue." (PMID 29867042, 2018). "A recent report in human pancreatic cancer cells indicated that CX3CL1 protects against apoptosis." (PMID 37770496, 2023). "Increased CX3CL1 promoted the recruitment of CX3CR1-expressing pancreatic tumor cells." (PMID 35478937, 2022). "Increased CX3CL1 promoted the recruitment of pancreatic tumor cells expressing CX3CR1." (PMID 35478937, 2022). "Pancreatic ductal adenocarcinoma cells bearing CX3CR1 specifically adhere to CX3CL1-expressing cells of neural origin and migrate in response to CX3CL1 produced by neurons and nerve fibers, contributing to perineural dissemination in pancreatic cancer." (PMID 21750716, 2011). "According to previous studies, CX3CL1 and its unique CX3CR1 receptor are involved in the progress of PNI in pancreatic cancer cells." (PMID 37799274, 2023). "CX3CL1 exclusive receptor CX3CR1 was expressed in different tumor such as breast, liver, prostate, and pancreatic cancer." (PMID 35478937, 2022). "From the previous reports, CX3CL1/CX3CR1 axis was involved in the pathogenesis of various types of tumors, including breast, gastric, lung, colorectal, and pancreatic cancer." (PMID 35478937, 2022). "The data showed that most of chemokines, such as CX3CL1, CXCL16, CXCL3, CXCL9, and CXCL5, were significantly high expressed in pancreatic tumor tissues compared to normal tissues." (PMID 35478937, 2022). "TRAIL resistant pancreatic cancer cell lines show a higher basal and inducible NF-κB activity compared to sensitive cell lines and TRAIL treatment induces CX3CL1 expression in these cells." (PMID 29867042, 2018). "The authors reported than three pancreatic cancer cell lines (Aspc-1, Capan-2 and MIA PaCa-2) upregulated the expression of the anti-apoptotic molecules BCL-2 and BCL-xl in response to exogenous CX3CL1; while the pro-apoptotic caspase 3 is decreased in response to CX3CL1 stimulation." (PMID 33391453, 2021). "This associates with an upregulated expression of the CX3CL1 receptor, CX3CR1, in pancreatic cancer specimen and therefore our array analysis prompted us to investigate whether the TRAIL-NF-κB mediated CX3CL1 expression directly affects the apoptosis resistance of PDAC cells." (PMID 29867042, 2018). "In the present study, we could not show a direct impact of CX3CL1 on TRAIL mediated apoptosis but provide instead strong evidence for a paracrine-signaling pathway which might contribute to the described protumorigenic action of CX3CL1 in pancreatic cancer cells." (PMID 29867042, 2018).